TRIM25 (tripartite motif containing 25)
Diseases named in the same sentence as TRIM25 in open-access papers (continued):
Sharing a sentence is not in itself a finding about the gene and the disease.
tumor (continued). "Again, the beneficial effects on tumor growth by TRIM25 knockdown were supposed to be mainly due to the upregulation of the negative cell cycle regulator 14-3-3σ." (PMID 39851496, 2025). "We further investigated the effect of the TRIM25/BRD7 axis on tumor growth and PTX resistance in vivo." (PMID 41315221, 2025). "The results showed that compared with the siNC group, TRIM25 knockdown slowed tumor growth and reduced tumor weight, whereas the recovery expression of BRD7 reversed the inhibitory effect of TRIM25 knockdown." (PMID 41315221, 2025). "At 28 days after implantation, tumor size was significantly smaller in TRIM25-knockdown groups compared to control groups." (PMID 38303029, 2024). "The interaction between IGF2BP3, TRIM25, and miR-3614 delineated a novel regulatory pathway crucial for tumor cell proliferation." (PMID 38338932, 2024). "Luciferase-expressing TRIM25-knockdown and control cell lines were orthotopically implanted in nude mice to monitor tumor growth." (PMID 38303029, 2024). "Taken together, recent evidence suggests that TRIM25 play a multifaceted role in tumor cells via substrate modification, particularly ubiquitination." (PMID 38303029, 2024). "Diverse functional investigations reveal that, in multiple cancer cell models, TRIM25 fortifies tumor cell survival." (PMID 37867509, 2023). "Together, these data suggest a permanent downregulation of caspase-7 in CRC by the TRIM25-dependent activation of hnRNPH1, which functionally contributes to the apoptosis resistance of tumor cells." (PMID 36611995, 2023). "TRIM25 is considered as a type of oncoprotein that plays a regulatory role in reactive oxygen balance; it also enhances tumor cell proliferation and drug resistance by promoting Keap1 degradation." (PMID 36012594, 2022). "In PCa, TRIM25 promotes cell proliferation and chemotherapy resistance, which can indirectly stabilize C-myc to enhance tumor development." (PMID 36012594, 2022). "TRIM25 takes part in tumor growth, metastasis, and chemoresistance with its ubiquitin ligase activities." (PMID 36199791, 2022). "Further, in a cohort of PTC patients, we observed higher expression of TRIM25 and PKCδ in the tumor and metastatic lesions, when compared to the matched normal tissue." (PMID 36217175, 2022). "In conclusion, this study provides a new method to define genes influencing tumor progression, and sheds light on the role of the defined TRIM25 in regulating glucose metabolism and promoting PCa malignancy." (PMID 36012594, 2022). "The protein levels of TRIM25 and caspase 3, a cell apoptosis-related protein, were increased, and the levels of Ku80 were decreased in the tumours of the USP44 group compared with those of the control group." (PMID 35079021, 2022). "In HCC xenograft mouse models, depletion of TRIM25 increases Keap1 and inactivates Nrf2, suppressing tumor growth." (PMID 36552825, 2022). "It has been shown that TRIM25 as a transcription factor involved in the progression of many tumor diseases." (PMID 33858324, 2021). "Mechanistically, circNDUFB2 functions as a scaffold to enhance the interaction between TRIM25 and IGF2BPs, a positive regulator of tumor progression and metastasis." (PMID 33436560, 2021). "In the present study, we revealed that TRIM25 was a significant predictor of poor prognosis in patients with CRC treated with OXA, and high expression of TRIM25 predicted tumor recurrence, suggesting that TRIM25 is involved in OXA resistance." (PMID 33966039, 2021). "One of the TRIM family members, TRIM25, participates in the regulation of biological processes, including tumor cell proliferation, invasion and migration." (PMID 33843442, 2021). "Representative IHC staining confirmed that TRIM25 levels were markedly increased in patients with CRC with tumor relapse." (PMID 33966039, 2021). "Our study indicates that OTUD5, a member of the ovarian tumor protease (OTU) subfamily of DUBs, cooperates with TRIM25 in tumor suppression via deubiquitination activity." (PMID 34102455, 2021).
tumor (continued). "To explore the potential role of TRIM25 in CRC therapy, we initially evaluated the TRIM25 level in 26 primary tumor tissues from patients with stage III CRC that were treated with OXA-based chemotherapy." (PMID 33966039, 2021). "The catalytic activity of OTUD5 is necessary for OTUD5 function, which is consistent with our findings that OTUD5 interacts with and deubiquitinates TRIM25 to inhibit tumor growth." (PMID 32826889, 2020). "To explore the mechanisms by which TRIM25 contributes to tumor development, we performed an unbiased transcriptome analysis by RNA sequencing (RNA-seq)." (PMID 32826889, 2020). "Our studies reveal a critical role of OTUD5 in tumorigenesis, as indicated through its interaction with TRIM25, suggesting that the OTUD5-TRIM25 axis acts as an important transcriptional regulator in tumor progression." (PMID 32826889, 2020). "Here, the authors show that TRIM25 is induced during ER stress and promotes tumour cell survival by targeting Keap1 for degradation, leading to Nrf2 activation." (PMID 31953436, 2020). "Briefly, OTUD5 potentially inhibits tumor progression by regulating PML transcription by deubiquitinating TRIM25." (PMID 32826889, 2020). "Functional investigation reveals that TRIM25 facilitates tumor cell survival by targeting Keap1 for ubiquitination and degradation, leading to activate Nrf2 signaling and reduce ROS levels during ER stress in several cellular models of cancers." (PMID 31953436, 2020). "Further, the OS data showed the patients with low TRIM25 or high SP1 expression alone in GC tumor tissues had poor OS than high TRIM25 or low SP1 ones." (PMID 32576271, 2020). "TRIM25 has been confirmed to be involved not only in the immune response against many RNA viruses but also in the occurrence of tumours in humans, as an important innate immune molecule." (PMID 33298177, 2020). "The TRIM25 levels in the HCC tumor tissues were significantly higher than those in normal liver tissues." (PMID 32826889, 2020). "In contrast, depletion of TRIM25 leads to ER stress and attenuates tumor cell growth in vitro and in vivo." (PMID 31953436, 2020). "Following subcutaneous injection for 5 weeks, the tumor volume of the TRIM25 overexpression group revealed a significantly higher progression trend compared with the control plasmid group." (PMID 28620119, 2017). "The median gene expression levels were elevated in IHC NF-κB – tumours compared to IHC NF-κB+ tumours for all ER target genes, except TRIM25." (PMID 17700572, 2007). "In a clear contrast, another study on human pancreatic cancer cell lines, by employing an unbiased drug screening aiming on the identification of novel tumor cell selective ferroptosis-inducing compounds, identified TRIM25 inducers as a valid therapeutic approach to overcome ferroptosis resistance." (PMID 39851496, 2025). "In line with its function as an RING-type of E3 ligase, therapeutic approaches which could specifically target the ligase activity of TRIM25 could be ideally used for (re)sensitizing tumor therapies." (PMID 39851496, 2025). "Accumulating evidence demonstrates that TRIM25 is a key player in tumor chemotherapy resistance." (PMID 41315221, 2025). "By addressing potential mechanisms underlying increased TRIM25 expression in NSCLC, a clinical study analyzing NSCLC tissues and adjacent normal tissues found elevated TRIM25 expression but low micro (miR) RNA-365 expression, mainly in tumor tissue." (PMID 39851496, 2025). "Additionally, we assessed the invasive capabilities of TRIM25-knockdown GBM#021 cells through a 3D tumor spheroid invasion assay." (PMID 38303029, 2024). "Colony formation assays further demonstrated the role of TRIM25 in promoting tumor proliferation." (PMID 38303029, 2024). "In addition, the IGF2BP3/tripartite motif containing 25 (TRIM25)/miR-3614 axis represents a new way to regulate tumor cell proliferation." (PMID 39054967, 2024). "In HCC, TRIM25 enhances tumor cell survival by targeting Keap1 for degradation." (PMID 38199981, 2024).
tumor (continued). "As an E3 ubiquitin ligase, TRIM25 needs interact with its substrate to promote tumor growth." (PMID 38303029, 2024). "Decreased Keap1 by TRIM25 activates Nrf2 and leads to tumor cell proliferation." (PMID 36552825, 2022). "In addition, decreased TRIM25 expression in tumor tissues were positively correlated with poor prognosis of GC patients." (PMID 33843442, 2021). "Taken together, these findings indicate that elevated levels of TRIM25 contribute to tumor progression, and serve as an important indicator for poor prognosis in several tumor types, especially HCC, thus providing a potential therapeutic target for cancer prevention." (PMID 31953436, 2020). "As a feedback mechanism, TRIM25 is required for tumor cells to defend against ER stress." (PMID 31953436, 2020). "Considering that TRIM25 deficiency in tumor cells leads to ER stress, which compromises tumor survival, we therefore determine whether TRIM25 is involved in the survival and adaptation of tumor cells to ER stress." (PMID 31953436, 2020). "However, TRIM25 markedly rescued the growth suppression as well as the pro-apoptotic phenotype of tumor cells induced by ER stress in the HCT116 and Huh7 cells." (PMID 31953436, 2020). "In addition, the OTUD5/TRIM25 double knockdown cells formed smaller tumor sphere than did the OTUD5-depleted cells, demonstrating that the OTUD5-TRIM25 axis plays an important role in the regulation of tumor growth." (PMID 32826889, 2020). "It is tempting to speculate that TRIM25, in addition to its reported degradative activity on let-7 precursors, may stabilize certain tumor cell-specific miRNAs." (PMID 31842382, 2019). "TRIM25 only has an elevated expression in either tumor cell lines or tumor tissues, indicating it might be a good drug target candidate." (PMID 28620119, 2017). "Among the upregulated genes, we identified several oncogenes (Ets2, Fyn, Fos, Rab30 and Src), various tumor markers (Cyp1b1, Gpa33, Cd47, Fam129a, st7l, chka, Lgalsbp, Antxr1 and Ly6a) and other genes related to tumor promotion (Cxcl10, Trim25, Grn, Foxc2, Bmp7 and Irs1)." (PMID 23936067, 2013). "Although this pathway is not directly related to apoptosis resistance, it adds an important novel facet to the complex repertoire of mechanisms by which TRIM25 can promote tumor development and may, therefore, highlight the estimated benefits of TRIM25-targeting therapies for cancer treatment." (PMID 39851496, 2025). "Moreover, we demonstrate that OTUD5 plays a previously unknown role in transcriptional regulation and tumor suppression by deubiquitinating TRIM25, leading to the downregulation of PML and fewer PML-NBs." (PMID 32826889, 2020). "If TRIM25 expression levels varied at different stages, it might tell us at which stage it is the time to treat patients with target TRIM25 drug, to repress primary tumor growth or inhibit the metastasis." (PMID 28620119, 2017). "Transcriptomic data were also retrieved from the International Cancer Genome Consortium, and following normalization, the Wilcoxon rank-sum test was used to compare TRIM25 expression between HCC tumors and matched adjacent non-tumor tissues." (PMID 41993211, 2026). "Subsequently, TRIM25 promotes the nuclear translocation of TFEB and transcription of autophagy-related genes by increasing its K63-polyubiquitination, thereby reducing tumor sensitivity to PTX." (PMID 38926803, 2024). "Immunohistochemical staining of sections from tumor xenograft models demonstrated reduced protein levels of PRMT1 and c-MYC in tumor xenografts derived from TRIM25-knockdown GBM#021 cells relative to controls." (PMID 38303029, 2024). "Previous studies have elucidated that TRIM21, TRIM26, TRIM35, TRIM50, and TRIM56 acted as tumor suppressors by inhibiting tumor cell proliferation, and TRIM3, TRIM16, TRIM21, TRIM25, and TRIM26 negatively regulated migration and invasion in HCC cells." (PMID 35142083, 2022).
tumor (continued). "Two of them (TRIM16 and TRIM50) are considered tumor suppressive, while others (TRIM11, TRIM25, TRIM27, TRIM52 and TRIM59) instead promote oncogenesis in this type of cancer." (PMID 34208621, 2021). "Supporting a role of TRIM25 in tumorigenesis, TRIM25 depletion in HCC cell line remarkably induces ER stress and impairs tumor cell growth in vitro and in vivo." (PMID 31953436, 2020). "The knockdown efficiency of OTUD5 and the levels of TRIM25 and PML in the tumor tissues formed by the OTUD5-depleted cells were determined by RT-PCR." (PMID 32826889, 2020). "Here we show that expression of E3 ligases (HERC5 and EFP/TRIM25), UBA1 and USP18 is significantly upregulated in HCC tumours compared to adjacent non-tumour liver tissues." (PMID 32132870, 2020). "Overexpression of TRIM25 was able to reduce CIC protein expression while siRNA knockdown of TRIM25 was able to stabilize CIC and promote its tumor suppressor function." (PMID 33115448, 2020). "Decreased TRIM25 expression and increased SP1 expression in tumor tissues were positively correlated with poor prognosis of GC patients." (PMID 32576271, 2020). "TRIM25 further degraded SP1 therefore reduces transcription and translation of MMP2, ultimately leading to reduction of angiogenesis and tumor proliferation in GC." (PMID 32576271, 2020). "Importantly, small-molecule screening identified T7117 as an inhibitor that disrupts the TRIM25-HIF-1α interaction, suppresses tumor growth, and enhances temozolomide efficacy." (PMID 42020378, 2026). "Meanwhile, compared with the siNC plus PTX group, TRIM25 knockdown significantly increased the anti-tumor effect of PTX, and restoring BRD7 expression could significantly reverse the effect of TRIM25 knockdown on paclitaxel chemotherapy." (PMID 41315221, 2025). "Functionally, knockdown of TRIM25 in CCA cells induced apoptosis, as confirmed by Annexin/PI staining and increased cleavage of PARP, Caspase-3, and Caspase-9, and furthermore, it suppressed growth of tumor cells." (PMID 39851496, 2025). "In tumor cells, OTUD5 promotes tumor progression by deubiquitinating TRIM25." (PMID 38880876, 2024). "Subsequently, TRIM25 promotes the nuclear translocation of transcription factor EB (TFEB) and transcription of autophagy related genes by increasing K63-polyubiquitination of TFEB, thereby reducing tumor sensitivity to PTX." (PMID 38926803, 2024). "G3BP1, EIF2AK2, TRIM25, and ACTA1 were among the top-ranked proteins, and these were closely related to tumor proliferation, metastasis, and invasion, suggesting that seRNA-NPCM may play a crucial role in NPC tumorigenesis and development." (PMID 37479693, 2023). "Collectively, TRIM25 binds with DHX9 and DDX5 to participate in RNA processing to downregulate TCA enzyme expression, thereby remodeling the TCA cycle and glycolytic flux is increased to promote tumor proliferation." (PMID 36012594, 2022). "Moreover, circNDUFB2 promotes ubiquitination degradation of IGF2BPs through forming a TRIM25/circNDUFB2/IGF2BPs ternary complex and recruits immune cells into the tumor microenvironment by activating the RIG-1-MAVS pathway, thus attenuating tumor progression." (PMID 35773744, 2022). "Finally, western blotting showed JP3 treatment up-regulated expression of TRIM25 and down-regulated expression of SP1 significantly in GC tumor tissues compared to the Ctrl-P-H treatment." (PMID 32576271, 2020). "The tumor spheres derived from the OTUD5-depleted cells and PML-depleted cells grew faster and had greater weight than those excised from the control cells, while TRIM25 knockdown inhibited tumor sphere formation." (PMID 32826889, 2020). "Besides, dysregulation in post-transcriptional modifications, like ubiquitination enzymes (HUWE1, CUL4A, TRIM25, etc.)and deubiquitination enzymes (USP7, USP10, USP24, etc.)in these PTC tumor samples may also lead to the low consistency." (PMID 38609408, 2024). "Conversely, forced expression of TRIM25 did not affect ROS levels in resting tumor cells." (PMID 31953436, 2020).
tumor (continued). "Data gathered in our study suggested only a mild activation of the PERK pathway was observed regardless of TRIM25 depletion or forced expression of TRIM25 upon ER stress in tumor cells, suggesting TRIM25 activates Nrf2 signaling that is independent of PERK pathway." (PMID 31953436, 2020). "Furthermore, TRIM25 downregulation reduced migration of EC cells in the absence of hormone treatment and stopped tumor growth in xenograft mouse models, suggesting that TRIM25 may slow down the transformation process in EC, independently of ERα signaling." (PMID 34208621, 2021). "Our finding indicates a novel mechanism of tumor-suppressive activities by caspase-2, and accordingly, inhibition of caspase-2-mediated NONO cleavage by TRIM25 may enrich the repertoire of transcriptional and posttranscriptional events." (PMID 39851496, 2025). "While the study highlighted TRIM25 as a potential target for RIPK3-dependent necrosis-related diseases, the possible impact of regulation of this particular cell death modality by TRIM25 on the therapy resistance of tumor cells has not been addressed so far and awaits further investigations." (PMID 39851496, 2025). "Importantly, in clear contrast to RKO cells, overexpression of TRIM25 in HEK cells had no comparable effects on caspase-2 levels, suggesting that the negative regulation of caspase-2 by TRIM25 could probably reflect a tumor-specific phenomenon." (PMID 31842382, 2019).